PIK3CA (phosphatidylinositol-4,5-bisphosphate 3-kinase catalytic subunit alpha)
Diseases named in the same sentence as PIK3CA in open-access papers (continued):
Sharing a sentence is not in itself a finding about the gene and the disease.
tumor (continued). "Few studies have assessed if copy number gain or amplification in PIK3CA may be associated with response, however here, we observed that PIK3CA copy number gains are largely exclusive of single point mutations and may be higher in pre-treatment tumours which had residual disease at surgery." (PMID 37758711, 2023). "Intriguingly, we observed very low SCGB2A1 expression coupled with a higher frequency of PIK3CA alterations in this tumor group." (PMID 37388735, 2023). "PTEN (57%), PIK3CA (48%), TIN (44%), and CLCN4 (6%), together with other genes with the highest mutation rates in the two groups, are displayed in the tumor’s abscissa in." (PMID 37671947, 2023). "As a PI3Kα selective inhibitor and mutant PI3Kα degrader, inavolisib can degrade mutant p110α protein without significantly altering wild-type p110α protein, so it can effectively improve the efficacy of PIK3CA mutant tumour patients." (PMID 37489050, 2023). "The tumor genome provided us with other therapeutic clues, such as PIK3CA and KRAS, which have corresponding targeted inhibitors." (PMID 36737820, 2023). "The mutation incidence in tumor samples was as follows: NF2 R57* (15/27), PIK3CA E545K (13/27), BRAF Hotspot mutations (10/27), SMO L412F (9/27), SMO W535L (7/27), with varying mutant allele frequencies represented by the dot sizes." (PMID 38259646, 2023). "PIK3CA activating mutation, encoding the p110α catalytic subunit of PI3K, is the most commonly mutated oncogene detected across tumor lineages." (PMID 37596643, 2023). "As a consequence of the mutant PIK3ca-mediated induction of cellular plasticity, transforming cells acquire characteristics of multipotent progenitors that contribute to tumor cell heterogeneity and mammary cancers with diverse pathological features." (PMID 38067308, 2023). "Next-generation sequencing identified genetic variations in these tumours, including MTOR gene mutations (4/5) and PIK3CA gene mutation (1/5)." (PMID 36816543, 2023). "Across 396 analyzed patients, prevalence of potentially actionable alterations was comparable with the expected prevalence in advanced disease (13% FGFR2/3, 20% PIK3CA, 13% ERBB2, and 37% with elevated tumor mutational burden ≥10 mutations/megabase)." (PMID 37601688, 2023).
tumor (continued). "To ensure the captured cells were truly tumor cells, we performed single cell analyses, which included whole-genome amplification, followed by the detection of mutations in the KRAS, BRAF, and PIK3CA genes, which are alterations representative of CRC." (PMID 36672711, 2023). "To understand the divergence in PIK3CA and NRAS, we analyzed the underlying tumor distributions in our dataset." (PMID 36658200, 2023). "Here, we present a case of a patient with advanced SqCLC that harbors not only CDKN2A mutation, and PIK3CA amplification, but also Tumor mutational burden High (TMB-H) and a tumor proportional score (TPS) of 50%." (PMID 36835617, 2023). "Four tumours had a MTOR gene exon 53 p.L2427Q mutation [c.7280T>A (p.Leu2427Gln)], and one tumour had a PIK3CA gene exon 10 p.E542K mutation [c.1624G>A (p.Glu542Lys)]." (PMID 36816543, 2023). "While most excess PIK3CA mutations were detected in tissue, discordant ESR1 mutations were balanced between tumor and plasma." (PMID 37511178, 2023). "Among those, only PIK3CA and FGFR3 mutations were already detectable in primary tumor tissues in 2/14 and in 2/2 samples respectively." (PMID 37064137, 2023). "In the exploratory analysis on PIK3CA mutations identified in circulating tumor DNA (ctDNA), the combination treatment was associated with an improvement in PFS compared with fulvestrant alone only in patients with PIK3CA mutations." (PMID 35565291, 2022). "The targeted therapies are tailored to the patient based on the specific genetic background of the tumor (e.g., mutation or altered expression of EGFR, KRAS, BRAF, PIK3CA, PTEN, HER2, or gene fusion of ALK, ROS1, RET)." (PMID 35205667, 2022). "comprehensively analyzed the genomic changes of 94 ESCC tumor samples through whole genome sequencing, and found that the amplification rate of PIK3CA in these samples was 38.3%(36/94)." (PMID 35392233, 2022). "Targeted NGS offers reliable and robust PIK3CA testing on both tumor and metastasis FFPE samples; the accuracy of RT-PCR depends on the DNA quantity and quality." (PMID 36428975, 2022). "Our study indicated the tumor‐promoting capacity of hypoxic glioma cell‐derived EVs harboring miR‐10b‐5p for glioma via upregulated PIK3CA and activated PI3K/AKT pathway through downregulating NEDD4L." (PMID 36052751, 2022). "N stage, tumor mutational burden (TMB), PIK3CA, and SF3B1 were identified as predictors to build the risk score model." (PMID 35562651, 2022). "One particular cluster of ATC tumours carried both BRAFV600E and the PIK3CA canonical hotspot mutations, with the E545K variant being the most common." (PMID 35193694, 2022).
tumor (continued). "The inhibition of these genes (dual EGFR/MEK and/or mTOR) resulted in a better response in tumor models exhibiting RAS family, BRAF or PIK3CA mutations." (PMID 36556139, 2022). "The collected tumor samples were used to perform RT-qPCR and western blotting, revealing markedly decreased PIK3CA mRNA and protein expression in the experimental group with circ-ZEB1 downregulation as compared with that in the Sh-NC group." (PMID 35277182, 2022). "The PIK3CA mutation status was available for 120 tumour samples of TNBC patients receiving NACT, 20 of them with a PIK3CA-mutation." (PMID 36279023, 2022). "Additional pathogenic mutations, including KRAS p.(Ala59Thr), PIK3CA p.(Thr1025Ala), and PIK3R2 p.(Lys564Glu), were identified in that particular stage-3 specimen, suggesting that the tumor is refractory to the anti-HER2 treatment." (PMID 36612265, 2022). "POLE ultra-mutated tumours exhibit few copy number aberrations and have mutations in PTEN, PIK3RI, PIK3CA, FBXW7 and KRAS genes." (PMID 35530346, 2022). "As a third case report, we present patient CRC-0042 (stage II) who had the following mutations detectable by sequencing of the original tumor: BRAF (N581I at 28.7% VAF), NRAS (G12V at 41.9%), and PIK3CA (E545K at 57.7%)." (PMID 36579573, 2022). "Further investigation revealed that high TME-score was also related with high expression of immunosuppressive molecules, decreased tumor mutation burden (TMB), and high rate of mutation in significantly mutated genes (SMGs) (e.g., PIK3CA and CDH1)." (PMID 35401704, 2022). "Of the transcriptional factors, CREB5, HIF1A, NFKB1, and PIK3CA, downregulation of NFKB1 and PIK3CA supports tumor growth and survival." (PMID 35967849, 2022). "One tumor (9%) carried a double NRAS mutation (Q61R and T58A) and one tumor (9%) carried a PIK3CA mutation (E542K)." (PMID 35624529, 2022). "The mutated PIK3CA gene activates the PIK3, initiating the tumor growth in breast tissues that comprised p85 and p110." (PMID 35684353, 2022). "PPA was highest in samples with a tumor fraction of >10%, especially for potentially actionable alterations in PIK3CA (93%) and BRCA1/2 (95%)." (PMID 36470901, 2022). "These cells harbor mutations in BRCA2, PIK3CA, PTEN, and ARID1A genes, among others, associated with tumor initiation." (PMID 36438565, 2022). "Activating mutations in PIK3CA, the gene encoding the p110α subunit of PI3K, occur in ~40% of breast cancers, and they are driver events for tumorigenesis and tumor progression." (PMID 36428975, 2022). "An in vivo study has shown that oncogenic MET/PIK3CA synergistically induces tumor aggressiveness and chemoresistance." (PMID 35621626, 2022). "All ipatasertib-treated patients with low immune scores and complete clinical response had PIK3CA/AKT1/PTEN-altered tumours." (PMID 36003779, 2022). "In both pools, the PIK3CA p.(Hys1047Arg) originally present in tumor tissue and ctDNA were detected." (PMID 35682999, 2022).
tumor (continued). "The VAF for PIK3CA G1049R in circulating cfDNA was increased by over 10-fold during follow-up, serving as evidence for increased tumor fraction." (PMID 35379811, 2022). "The same group also showed that tumor growth was reduced by single targeting of ERBB2 in cetuximab-resistant, quadruple (i.e., KRAS, NRAS, BRAF, and PIK3CA) wt CRC patient derived xenografts with ERBB2 mutations." (PMID 35582524, 2022). "Next, we conducted a survival analysis in mice with only tumor‐related deaths in PIK3CA E545K subgroups." (PMID 34748271, 2022). "In tumor number 1052, a deletion was found in PIK3CA that resulted in the truncation of its transcript." (PMID 35343095, 2022). "The analysis indicated that six genes (PIK3CA, CDC27, B2M, PTEN, SMAD4, and IL32) were strongly associated with tumor-infiltrating lymphocytes." (PMID 35903675, 2022). "In contrast, in SHR-negative larger tumours (≥ 2 cm), patients with PIK3CA- mutations (n = 14) showed a trend to better 5 years-RFI probability (85.7%) compared to those with wildtype PIK3CA (5 years RFI 66.1%, HR 2.75; 95% CI 0.657–11.527)." (PMID 36279023, 2022). "Results showed that circulating tumor cells have not only the same mutated driver genes (such as APC, KRAS, or PIK3CA) with the primary and metastatic lesions but also new variant genes." (PMID 35799608, 2022). "All the PIK3CA mutated tumors were also sensitive to alpelisib except PDX287.3, which was derived from a patient’s tumor that progressed while being treated with the PI3Ki GDC-0032 plus letrozole." (PMID 36071033, 2022). "At the molecular level, these tumor characteristic mutations included PTEN (88%), RPL22 (33%), KRAS (35%), PIK3CA (54%), PIK3R1 (40%), and ARID1A (37%) with high TMB levels (18 × 106 Muts/Mb) and certain TIL." (PMID 36578004, 2022). "Recurrent tumor presented the following set of mutations: H3F3A (c.344C > G; p.Ala115Gly), PIK3CA (c.2119G > A; p.Glu707Lys), NF1 (c.7026G > T; p.Leu2342=) and DOCK6 (c.1664C > T; p.Pro555Leu)." (PMID 36611369, 2022). "PIK3CA is a key enzyme in the PI3K signaling pathway that regulates the cellular functions of tumor cells." (PMID 35212617, 2022). "Tumor organoids harboring KRAS, NRAS, BRAF, or PIK3CA hotspot mutations exhibited a relatively higher IC50 and area under the drug response curve (AUC) for cetuximab than organoids without hotspot mutations in these genes." (PMID 34850547, 2022). "In vivo, ABT-263 or A-1331852 in combination with radiation decreased tumor growth and increased tumor-tripling time (P < 0.0001) in PIK3CA/PTEN wild-type TNBC cell line and patient-derived xenografts." (PMID 36381235, 2022). "Clinically, upregulated PIK3CA expression was significantly related to neoplasm invasiveness, poor patient survival and lymph node metastasis." (PMID 36539659, 2022). "PIK3CA-mutations were significantly more frequent in steroid hormone-receptor (SHR)-positive HER2-negative (31.4%), and G1 and G2 tumours (32.8%)." (PMID 36279023, 2022).
tumor (continued). "Similar to our in vitro studies, sulindac led to significant tumor growth inhibition only in the PIK3CA-MT PDX model." (PMID 35158773, 2022). "The drug combination induced tumor regression of xenografts established from DLD1 cells, which harbor a PIK3CA E545K mutation, whereas single drugs alone only slowed tumor growth." (PMID 35418124, 2022). "In tumours with high risk biology (HER2-positive, TNBC) we found the lowest rate of PIK3CA-mutations (15.2% and 11.4), which is also consistent with published data." (PMID 36279023, 2022). "The combination of Alpelisib and Tazemetostat induced tumor regression of Vaco481 CRC cells with a PIK3CA Q546P mutation and a CRC PDX harboring a PIK3CA E542K mutation." (PMID 35418124, 2022). "Capivasertib, a potent selective inhibitor of all three AKT isoforms, in combination with fulvestrant shows clinical activity in patients with ER+/HER-negative BC, including those with PIK3CA/AKT1/PTEN mutant tumours." (PMID 36241868, 2022). "Phosphatidylinositol-3-kinase (PI3K) (gene symbol PIK3CA) intracellularly mediates different processes like promoting cell transformation, tumour initiation and proliferation, and resistance to apoptosis." (PMID 36279023, 2022). "14/27 (52%) patients had PIK3CA detected in peripheral blood (Guardant 360 testing), and 13/27 (48%) had PIK3CA detected on tumor tissue (Omniseq, Foundation One)." (PMID 36338738, 2022). "In preclinical studies, treatment with taselisib described marked tumor suppressing effect on PIK3CA-mutant xenografts models." (PMID 35565291, 2022). "Oncogenic PIK3CA mutations contribute to tumorigenesis by activating AKT signaling to decrease apoptosis and increase tumor invasion." (PMID 36128324, 2022). "While the parental LAMEV cell line expressed all four markers, the edited LAM1:PIK3CAE545K cells expressed significantly lower levels of all four markers, suggesting that the tumours expressing activated PIK3CA were more poorly differentiated." (PMID 35193694, 2022). "Aligned with the tumor growth kinetics, immunostaining (immunohistochemistry, (IHC)) showed that in PIK3CA wild type Cal27 cells, inhibition of HER3 by CDX-3379 decreased pS6, which correlated with decreased proliferation as depicted by BrdU incorporation." (PMID 33888713, 2021). "The cohort of patients now reported comprehends those young patients who had FFPE tumor samples available for PIK3CA analysis." (PMID 34287479, 2021). "Our data indicated a benefit of aspirin usage particularly for patients with combined wild-type PIK3CA and mutated-KRAS tumor characteristics." (PMID 34638442, 2021).